TIGIT (T cell immunoreceptor with Ig and ITIM domains)
Diseases named in the same sentence as TIGIT in open-access papers (continued):
Sharing a sentence is not in itself a finding about the gene and the disease.
COVID-19 (continued). "During some acute viral infections (e.g., flu or COVID-19), PD1 as well as other ICPMs, such as LAG3, TIM3, TIGIT, and CD200, are up-regulated." (PMID 38793691, 2024). "We aimed to perform in-depth immunophenotyping of major cell subsets present in human peripheral blood of COVID-19 patients and controls using PD1, TIM3, LAG3, TIGIT, and CD200R, as well as CD39, as markers for the purinergic signaling pathway." (PMID 38793691, 2024). "Considering the distinct function of TIGIT+Tregs in favoring Th2 immunity, and that COVID-19 patients in ICU present signs of Th2-biased immunity, we speculate that worse COVID-19 outcomes could be associated with impaired microbicidal immunity due to TIGIT+Tregs expansion." (PMID 37604833, 2023). "Although the diminished TIGIT+ and TIGIT− FOXP3+ T regulatory cells count in the blood of COVID-19 patients independently of their respiratory status, their proportion of both TIGIT+ and TIGIT− FOXP3+ T regulatory cells subsets were strongly disturbed." (PMID 37604833, 2023). "Vδ2Vγ9T cell clusters 20 and 25 from CR2 panel were expanded in severe and critical COVID-19 (Bonferroni-adjusted P-value range 0.00564–6.39 × 10−8) and characterized by CCR9, CXCR3 and TIGIT expression." (PMID 36433939, 2022). "Based on the analysis of PBMC in COVID-19-infected patients, CD8+ T cells exhibit an exhausted phenotype characterized by the surface expression of TIGIT, TIM-3 and/or PD-1." (PMID 36334153, 2022). "In the acute phase of severe COVID-19, a considerable proportion of SARS-CoV-2-specific CD8+ T cells express TIM-3, LAG-3, TIGIT, and CTLA-4." (PMID 34413488, 2021). "Next, we examined the expression of the inhibitory receptors PD1, TIGIT, LAG-3, TIM-3, and BTLA of T cells in COVID-19 and malaria compared to healthy controls." (PMID 32983106, 2020). "Furthermore, in COVID-19 patients, there is an observed upregulation in the expression of immune checkpoint molecules such as PD-1, CTLA-4, TIM-3, LAG-3, TIGIT, and VISTA." (PMID 39967737, 2025). "Prior findings reported that, in COVID-19, especially in severe patients, activation and exhaustion markers on the T cell surface were upregulated during acute infection, such as CD69, OX40, CD38, 4-1BB, PD-1, CTLA-4, LAG-3, TIM-3, and TIGIT." (PMID 39355257, 2024). "Additionally, the expression of transcripts regulating cellular exhaustion (TIGIT, BTL4, PDCD1, and HAVCR2) was found to be similarly upregulated in severe COVID-19." (PMID 37029220, 2023). "Interestingly, we detected a small population of exhausted CD8+ T cells (TEX) characterized by expression of TIGIT, CTLA4, CD279 (PD-1) and HAVCR2 (Tim-3) that was exclusive to the severe COVID-19 group, a finding which has been reported by others before." (PMID 36591270, 2022). "Among the co-inhibitory receptors, LAG3, CTLA4, and HAVCR2 were enriched in CD8+ T cells from COVID-19 patients that eventually succumbed to the disease, but PDCD1 and TIGIT were enriched in CD8+ T cells from COVID-19 patients that eventually recovered and discharged." (PMID 36119105, 2022). "We did not detect increased TIGIT expression on bulk T cells in COVID-19 patients compared to healthy controls." (PMID 32983106, 2020). "To see whether similar effects can be observed in COVID-19, we assessed the frequencies of the co-inhibitory receptors PD1, TIGIT, BTLA, LAG-3, and TIM-3 on CD8+ and CD4+ T cells in COVID-19 and malaria patients and compared them with healthy individuals." (PMID 32983106, 2020). "As elevated serum levels of TIGIT and IL-10 have been documented in SARS-CoV-2 infection, the attenuated polio vaccine may be beneficial against COVID-19, as it inhibits CD155 and its immunosuppressive network." (PMID 32655579, 2020). "Notably, the expression of T-cell activation and exhaustion markers CD137, OX40, and TIGIT have not been previously reported in PWH with acute COVID-19." (PMID 38408318, 2024).
COVID-19 (continued). "Also, the expression of PD-1 and TIGIT on CD4+ T cells did not correlate with the level of humoral and cellular response against COVID-19." (PMID 39355257, 2024).
acute myeloid leukemia (36 papers, 2017 to 2026). Acute myeloid leukemia (AML) is a group of neoplasms arising from precursor cells committed to the myeloid cell-line differentiation. "High TIGIT expression on peripheral CD8+ T cells is associated with primary refractory disease in acute myelogenous leukemia (AML) patients." (PMID 34367161, 2021). "T cell immunoglobulin and immunoreceptor tyrosine-based inhibitory motif (ITIM) domain (TIGIT) and programmed cell death protein 1 (PD-1) are important inhibitory receptors that associate with T cell exhaustion in acute myeloid leukemia (AML)." (PMID 28629373, 2017). "TIGIT has also been implicated in other heme cancers, such as follicular lymphoma (FL) and acute myeloid leukemia (AML)." (PMID 35812451, 2022). "Even if their functional potential has been much less studied compared to that in T cells, in acute myeloid leukemia (AML), it was recently found that a higher frequency of TIGIT+ NK cells in the blood was associated with a poorer prognosis." (PMID 34884723, 2021). "Moreover, TIGIT expression has been associated with tumor growth in diverse cancers, including chronic lymphocytic leukemia and acute myeloid leukemia (AML)." (PMID 39939322, 2025). "In acute myeloid leukemia pts, TIGIT-expressing T cells exhibited a considerable level of apoptotic marker Annexin V." (PMID 39858045, 2025). "A transcription factor Eomesodermin (Eomes) is expressed on CD8+ T cells of patients diagnosed with acute myeloid leukemia, and it can enhance the expression of TIGIT by binding to its promoter region." (PMID 35720417, 2022). "Interestingly, high frequencies of TIGIT+ CD8+ T cells are also detected in patients with acute myeloid leukemia (AML) and are associated with poor clinical outcome." (PMID 29755666, 2018). "Our previous study revealed that the altered expression of immune checkpoint T-cell immunoreceptor with immunoglobulin and ITIM domain (TIGIT) on γδ T cells may result in immunosuppression and is possibly associated with a poor overall survival in acute myeloid leukemia (AML)." (PMID 38711501, 2024). "However, in acute myeloid leukemia, a unique CD8+ T cell subset that expressed PD-1 and TIGIT but displayed lower levels of DNAM-1 has been linked to failure to achieve remission after induction chemotherapy." (PMID 39201462, 2024). "γδTregs, a new subset of Tregs, has been reported that higher TIGIT+ γδTregs contributed to the poorer overall survival in patients with acute myeloid leukemia, suggesting that TIGIT may be involved in regulating Treg cells in malignancies." (PMID 35433470, 2022). "The proportion of TIGIT+CD8+T cells is increased in peripheral blood collected from acute myeloid leukemia (AML) patients, and it becomes more evident in patients with primary refractory disease and leukemia relapse post-allogeneic stem-cell transplantation." (PMID 33670993, 2021). "Given the significant immune-permissiveness of NK cells circulating in acute myeloid leukemia (AML) patients, we asked whether adoptive transfer of activated NK cells would benefit from additional TIGIT-blockade." (PMID 38967649, 2024). "In acute myeloid leukemia (AML) patients, elevated TIGIT expression on CD8+ T cells was observed." (PMID 36605439, 2022). "In acute myeloid leukemia, it has been reported that EOMES binds to the promoter of TIGIT and up-regulates the expression of this inhibitory receptor on patient-derived T cells." (PMID 34975867, 2021). "Notably, TIGIT and CD39 were shown to be upregulated in PB NK cells from patients with acute myeloid leukemia and in esophageal squamous cell carcinoma, respectively, suggesting specific IC regulation mechanisms that depend on the tumor type." (PMID 41148229, 2025). "TIGIT blockade can stimulate phagocytosis by repolarizing M2-type macrophages to M1-type macrophages, synergizing with CD47 antibodies that block the "don’t eat me" signal, inducing macrophage phagocytosis of acute myeloid leukemia (AML) cells." (PMID 40821806, 2025).
acute myeloid leukemia (continued). "Previous studies have also characterized the expression profiles of TIGIT and its family molecules on NK cells in other hematologic malignancies, such as myelodysplastic syndromes (MDS) and acute myeloid leukemia (AML)." (PMID 40231264, 2025). "Notably, upregulation of TIGIT has been observed in various malignancies, including melanoma, breast cancer, non-small-cell lung carcinoma (NSCLC), colon adenocarcinoma, gastric cancer, multiple myeloma (MM), and acute myeloid leukemia (AML)." (PMID 37569880, 2023). "In contradistinction, the introduction of TIGIT inhibitors could reprogram TIGIT+ M2 macrophages to the M1 phenotype, leading to increased CD47-mediated phagocytosis and ultimately benefiting the prognosis of patients with acute myeloid leukemia (AML)." (PMID 37291608, 2023).
glioblastoma (35 papers, 2019 to 2025). The most malignant astrocytic tumor (WHO grade IV). "The TIGIT/CD155 axis is critical for glioblastoma’s immune evasion, yet targeting TIGIT alone has proven ineffective." (PMID 40223940, 2025). "The syn notch-engineered pluripotent stem cell-derived NK cells that co-target CD73 and TIGIT/CD155 were effective mediators of anti-glioblastoma response and represented a powerful allogeneic treatment option for this tumor." (PMID 39188712, 2024). "In contrast, an optimized effect of dual-modified TIGIT-knockout-CAR-NK cells was reported in glioblastoma, which interestingly agrees with our results for the KLRC1KO of CAR-NK cells in AML51." (PMID 39349459, 2024). "The association of TIGIT expression with IDO and PD-L1 has also been observed in the tumor core of glioblastoma (GBM), underlining the necessity to further study the correlation between these proteins." (PMID 36874131, 2023). "Coexpression of TIGIT and PD-1 on CD8+ TILs, which is associated with dysfunctional antitumor immune responses, has also been observed in cancers such as HCC, glioblastoma (GBM), acute myeloid leukemia, NSCLC, and melanoma." (PMID 37928556, 2023). "Currently, an anti-TIGIT candidate in combination with an anti-PD-1 antibody is being evaluated for the application for recurrent glioblastoma." (PMID 36874131, 2023). "PD-L1 and TIGIT co-blockade also led to a significant survival benefit in a glioblastoma model, with 17% of mice showing long-term survival." (PMID 35327475, 2022). "Dual PD-1 and TIGIT blockade treatment in glioblastoma multiforme (GBM) patients showed decreased effector T cell function, increased Tregs, and increased tumor infiltrating dendritic cells (TIDCs)." (PMID 36159789, 2022). "It has been proposed that distinct co-inhibitory mechanisms are involved; besides the PD-L1/PD-1 axis, LAG3 and, more recently, TIGIT have been detected in glioblastoma T-cells." (PMID 32899203, 2020). "Anti-TIGIT antibody, so far employed in preclinical studies only in combination with anti-PD-1 antibody, showed promising results in glioblastoma animal models since an increased survival was observed and correlated with the infiltration of effector T cells in the tumor." (PMID 33920505, 2021). "In cancer, TIGIT has been detected in glioblastoma TME, mostly localized in the tumor core and TIL." (PMID 33920505, 2021). "Furthermore, combined treatment of TIGIT and PD-1 mAb had achieved good therapeutic effects in other cancers, such as glioblastoma, head and neck squamous cell carcinoma and renal cell carcinoma." (PMID 34659197, 2021). "Notably, TIGIT has demonstrated the capacity to dampen T-cell activation and proliferation, and TIGIT blockade has exhibited encouraging outcomes, resulting in enhanced antitumor immunity and prolonged survival, particularly in glioblastoma." (PMID 38342925, 2024). "This strategy shifts TIGIT/CD155 interactions towards activation, boosting NK cell cytotoxicity and achieving complete tumor eradication in glioblastoma models." (PMID 40223940, 2025). "Usurping activities of TIGIT and CD73 promotes the function of adoptively transferred NK cells into intracranial patient-derived models of glioblastoma and enhances their natural cytolytic functions against this tumor to result in complete tumor eradication." (PMID 38429294, 2024). "In line with our study, intratumoral T cells in glioblastoma were recently found to express multiple immune checkpoints, including PD1, TIM3, LAG3, TIGIT, and CD39, signs of a severe exhaustion signature amidst T cells." (PMID 36497232, 2022). "Our data show that synNotch-engineered pluripotent stem cell-derived NK cells are not only effective mediators of anti-glioblastoma responses within the setting of CD73 and TIGIT/CD155 co-targeting, but represent a powerful allogeneic treatment option for this tumor." (PMID 38429294, 2024). "This study demonstrates that TIGIT/CD155 and CD73 are targetable receptor partners in glioblastoma." (PMID 38429294, 2024).
glioblastoma (continued). "TIGIT/CD155 and CD73 were targeted receptor partners in glioblastoma." (PMID 39188712, 2024). "The cell exhaustion marker TIGIT was more abundant on lymphocytes of glioblastoma patients in comparison to HC and RRMS patients, on CD4+ lymphocytes of glioblastoma patients compared to HC, and on NK cells of glioblastoma in relation to RRMS patients." (PMID 39497174, 2024). "Even though we could not detect higher levels of PD-1 on lymphocytes in glioblastoma patients, these cells displayed higher TIGIT-MFIs, which presents another common Tc exhaustion marker, compared to controls." (PMID 39497174, 2024). "This may not be the case for all cancers, as TIGIT and CD226 were co-expressed in glioblastoma multiforme and in melanoma." (PMID 37596248, 2023).
glioma (32 papers, 2019 to 2025). A benign or malignant brain and spinal cord tumor that arises from glial cells (astrocytes, oligodendrocytes, ependymal cells). "Clinical trials are emerging that evaluate the efficacy of multiple immune checkpoint inhibitors for glioma, including blocking of TIGIT." (PMID 38438420, 2024). "This heightened expression suggests a potential role in tumor progression and aggressiveness, underscoring TIGIT's involvement in the immunosuppressive microenvironment typical of high-grade gliomas​." (PMID 38342925, 2024). "Signature scores of immune checkpoints, including CTLA4, LAG3, PDCD1, PD-L1, PD-L2 and TIGIT as well as the top five marker genes within each TAM subset were calculated using RNA-seq data from TCGA low grade glioma patients." (PMID 38515213, 2024). "In gliomas, the expression of immune checkpoint gene TIGIT (T-cell immunoreceptor with Ig and ITIM domains) is significantly elevated, correlating with advanced disease stages." (PMID 38342925, 2024). "MAPK4 expression was significantly positively correlated with expression of the main immunoinhibitory checkpoint molecules PD‐1, PD‐L1, HAVCR2, PDCD1LG2 and TIGIT in glioma." (PMID 36999945, 2023). "MDSCs have also been found to express PD-1, PD-L1, and T-cell immunoglobulin and ITIM structural domain protein (TIGIT) ligands in human glioma tissues, thereby blocking TIGIT/PD1 to restore T-cell proliferation and immune function." (PMID 35854339, 2022). "Our data show, that compared with isotype treatment, both αTIGIT monotherapy and dual blockade of TIGIT & PD1 significantly reduced the frequencies of GL261 glioma infiltrating MDSCs (CD45+CD11b+Gr1+ cells), most strikingly for αTIGIT/αPD1 combination therapy." (PMID 34025646, 2021). "Previous studies revealed an elevated expression of CD155 on human glioma cells and an increased TIGIT expression in patient-derived CD8-positive TILs, which offers this signaling pathway as a potential therapeutic target." (PMID 34298735, 2021). "Previous studies demonstrated elevated levels of TIGIT expression in human gliomas; however, the therapeutic effects of targeting this pathway in glioma patients remain poorly understood." (PMID 34025646, 2021). "Together, our data reveal a mechanism of TIGIT/PD1 blockade in glioma and suggest distinct roles of these ICs on MDSC subsets and in regulating tumor immunity." (PMID 34025646, 2021). "Blocking TIGIT and PD-1 in a murine glioma model resulted in an increase in IFN-γ-expressing CD8-positive T cells and a decrease in Tregs in the brain, as well as an improved overall survival." (PMID 34298735, 2021). "Furthermore, we found that 5 immune inhibitors (KDR, TIGIT, VTCN1, LAG3 and ADORA2A) and 2 immune stimulators (ICOS and TNFRSF25) were significantly associated with HIC2 in gliomas." (PMID 36650953, 2023). "Moreover, glioma cells express increased levels of immunosuppressive factors such as PD-L1, TIGIT, CD96, and CTLA-4, which negatively regulate presentation of antigens and T-cell responses." (PMID 35281049, 2022). "In the present work, most of these exhaustion markers [TIGIT, CEACAM1, CTLA4, LAG3, PD-1, PD-L1, and TIM3] were highly expressed in the high-risk subtype, indicating an elevated level of immune exhaustion in the tumors of high-risk glioma patients." (PMID 34778248, 2021). "The opposing pattern of TIGIT expression in glioma and MS patients hints that anti-TIGIT therapy may indeed be beneficial for patients with GBM." (PMID 34298735, 2021). "Some other immune checkpoints, including CTLA-4, CD47, CD73, TIGIT, and CD137 were also studied in either clinical trials or preclinical research for gliomas." (PMID 39851525, 2025). "Our data revealed a significant correlation between the expression levels of immune checkpoint molecules (CD274, CTLA4, HAVCR2, LAG3, PDCD1, PDCD1LG2, TIGIT, and SIGLEC15) and RAB32 in high-grade gliomas (HGG)." (PMID 39668831, 2024).